ALB (albumin)
Diseases named in the same sentence as ALB in open-access papers (continued):
Sharing a sentence is not in itself a finding about the gene and the disease.
Hypoalbuminemia (continued). "Patients suffering from ALF often present with severe hypoalbuminemia, thus implantation of albumin-synthesizing cells may aid faster recovery." (PMID 35308825, 2021). "Besides hypoalbuminemia, potentially requiring a higher protein intake, albumin glycation is present in T2D." (PMID 34444908, 2021). "The occurrence of HA in patients with scrub typhus seems to be multifactorial; poor dietary intake, decreased synthesis of albumin due to hepatic dysfunction, increased catabolism of protein, and proteinuria are all known to be related to hypoalbuminemia in cases of acute infectious disease." (PMID 33630937, 2021). "Previous studies found that hypoalbuminemia was predictive for respiratory failure in MERS-CoV, and it may be considered that albumin drop is linked to liver failure." (PMID 33956870, 2021). "The effects of albumin in infectious disease are predominantly indirect and hypoalbuminemia may reflect the poor health of the patient." (PMID 33925831, 2021). "This information becomes more significant in patients with COVID-19, wherein increased levels of TNF-alpha and IL-6 may directly decrease albumin production and lead to hypoalbuminemia." (PMID 34683480, 2021). "IL-1, IL-6 and TNF-α, which are highly expressed in the serum of patients with hepatic alveolar echinococcosis, can inhibit the synthesis of ALB, which also leads to hypoalbuminemia; On the other hand, lymphocytes play an important role in immune monitoring and immune mediation." (PMID 34248983, 2021). "Hypoalbuminemia stimulates synthesis, whereas albumin infusion suppresses it." (PMID 34836265, 2021). "Severe hypoalbuminemia, with albumin levels <2.0 g/dL, was noted in 7 dogs." (PMID 33805804, 2021). "However, the furosemide dose-response in patients with hypoalbuminemia and the diuretic response when in combination with albumin warranted further examining." (PMID 34851962, 2021). "In the current study, we found that preoperative anemia was an independent modifiable risk factor for HA administration after THA, regardless of pre-ALB < 35 g/L or not, which has been confirmed before that anemia was associated with hypoalbuminemia." (PMID 34717693, 2021). "Nevertheless, the combined use of IL-15 values with albumin to predict mortality in COVID-19 is unexplored, even though hypoalbuminemia is a common laboratory finding in patients with severe illness, and IL-15 belongs to the cytokine storm that is frequently associated with disease lethality." (PMID 34683480, 2021). "Mean albumin was 3.3 ± 0.6 g/dL, with more than half of patients with hypoalbuminaemia." (PMID 34640538, 2021). "Calcium ion which circulates in plasma bound to albumin may mimic a false low level in presence of hypoalbuminemia despite normal ionized calcium levels." (PMID 34595082, 2021). "Therefore, patients with liver disease do not only suffer from hypoalbuminemia, but a larger proportion of their remaining albumin is dysfunctional." (PMID 34836265, 2021). "In our cohort, a significant number of YAAGC with peritoneal metastases were included, and the accumulation of albumin in peritoneum activity may thus have a role in hypoalbuminemia." (PMID 34568007, 2021). "Moreover, hypoalbuminemia reduces the amount of zinc bound to albumin in the blood, leading to increased urinary excretion of zinc." (PMID 33974681, 2021). "Although hypoalbuminemia is not identified as an independent risk factor of nosocomial pneumonia, many patient-related risk factors are characterized by low serum albumin levels associated with acute or chronic severe disease and comorbidities." (PMID 33925831, 2021). "The pathophysiology behind hypoalbuminemia in these situations includes decreased protein synthesis, decreased half-life, and the total amount of serum albumin, increased capillary permeability, the volume of distribution, and expression vascular endothelial growth factor." (PMID 33481913, 2021).
Hypoalbuminemia (continued). "Secondly, the negative association between HbA1c and albumin has a threshold effect and the association was stronger in the HbA1c-defined diabetic population with hypoalbuminemia." (PMID 34055818, 2021). "A systematic review with sequential analysis of all-cause mortality from major trials like SAFE, ALBIOS, and EARSS concluded that human albumin solutions did not reduce all-cause mortality in sepsis of any severity, even in patients with hypoalbuminemia." (PMID 34917416, 2021). "In small animals, intravenous albumin is mostly used to correct hypoalbuminemia and COP." (PMID 34277747, 2021). "Our results also showed that severe hypoalbuminemia existed in critical patients with COVID-19 at day 2-3 after admission and lower albumin level at last test before the achievement of clinical outcome in a non-survival patients group compared with that in survival cases." (PMID 34248834, 2021). "Elderly patients during the perioperative period of PLIF are likely to get hypoalbuminemia, which is usually accompanied by other systemic diseases and a decrease in organ activities, especially in the ability of the liver to produce and metabolize albumin." (PMID 34717707, 2021). "It is highly unlikely that hypoalbuminemia during acute infection might be related with reduced synthesis, due to the long half-life of albumin." (PMID 34768653, 2021). "Hypoalbuminemia is indicative of an increased catabolism related to an inflammatory systemic response, suppression of albumin synthesis and an increased vascular permeability followed by a shift of albumin from the intravascular sector towards the interstitium." (PMID 34884980, 2021). "Hypoalbuminemia is associated with poor prognosis in critically ill AKI patients with CRRT; therefore, measuring albumin may be helpful for predicting the prognosis." (PMID 34496793, 2021). "If profound hypoalbuminemia and hypotension are present, albumin transfusion can be considered." (PMID 33718468, 2021). "They propose that monitoring serum albumin levels may identify early postoperative hypoalbuminemia and aid in the early detection and prevention of AKI." (PMID 33945514, 2021). "However, in patients with hypoalbuminemia the incidence of CVEs was approximately 2-fold higher (4.39%/100 patient-year) compared to those with normal albumin levels (2.24%/100 patient-year)." (PMID 34239442, 2021). "However, breakdown of albumin is also increased in inflammatory states, which can lead to hypoalbuminemia." (PMID 33925831, 2021). "Of note, 14 of 24 patients underwent albumin supplementation due to hypoalbuminemia." (PMID 34537036, 2021). "Nonetheless, it is still unclear whether the unfavorable impact of hypoalbuminemia in the early phase of acute coronary syndrome reflects the state of inflammation or an independent effect of albumin itself." (PMID 36341223, 2021). "Blood work revealed hypoalbuminemia (albumin 2 g/dl), and hypogammaglobulinemia." (PMID 34006223, 2021). "On hospital admission, neutrophilia (neutrophil count ≥ 6.3 × 109/L), lymphopenia (lymphocyte count < 0.8 × 109/L), eosinopenia (eosinophil count < 0.02 × 109/L) and hypoalbuminemia (level of albumin < 30 g/L) were detected in 41 (55.4%), 52 (70.3%), 62 (83.8%) and 26 (35.6%) patients, respectively." (PMID 33526981, 2021). "Primary nephrotic syndrome (PNS) is a syndrome of glomerular diseases caused by a variety of etiologies, with increased levels of proteinuria (>3.5 g/24 h), hypoalbuminemia (serum albumin<30 g/L), and hyperlipidemia and varying degrees of edema being the main manifestations of the clinical syndrome." (PMID 34840588, 2021). "The observed regulation of lipotoxicity by albumin may be particularly relevant in coronavirus disease 2019 (COVID-19) patients with obesity and significant hypoalbuminemia." (PMID 33925831, 2021).
Hypoalbuminemia (continued). "Human albumin was given to counter the severe hypoalbuminemia, and the turtle was hospitalized for 2 months prior to detection of candidemia; these factors might have increased the risk of infection." (PMID 34944256, 2021). "Hypoalbuminemia was defined as a serum albumin concentration of ≤ 4.0 g/dL." (PMID 34050200, 2021). "Severe hypoalbuminemia was common; more than half had serum albumin < 2.5 g/dL at admission." (PMID 33597024, 2021). "A study of patients aged 90 or more hospitalized with acute infection showed that 70 patients (43.2%) had hypoalbuminemia with a serum albumin level of less than 35 g/L and that the albumin level was independently associated with in-hospital mortality (OR: 0.86, 95% CI = 0.78–0.95, p = 0.004)." (PMID 34433419, 2021). "Clinically, hypoalbuminemia was defined as a serum albumin <35 g/L." (PMID 34526075, 2021). "A total of 109 patients (60.2%) had hypoalbuminemia (albumin level < 3.3 g/dL)." (PMID 33725003, 2021). "Hypoalbuminemia (defined by a serum albumin <35 g/L) may result in edema of intestinal mucosa among patients, which might affect the engraftment of microbiota." (PMID 34746161, 2021). "Human albumin was administered to treat severe hypoalbuminemia." (PMID 34944256, 2021). "On the way to a more individualized medicine, hypoalbuminemia may serve as a parameter in future decision making for or against the use of albumin in volume therapy." (PMID 34618163, 2021). "In addition, hypoalbuminemia (albumin < 3.5), pN+, positive lymphatic invasion, and undifferentiated adenocarcinoma were frequent among patients in the high SII group (p = 0.014, 0.003, 0.004, and 0.022, respectively)." (PMID 34118953, 2021). "First, albumin has specific antioxidant functions because of its structure, and hypoalbuminemia may result in cellular oxidative damage and apoptosis." (PMID 34616765, 2021). "The mean time to infection manifestation was 10 days and the duration of hospital stay was negatively correlated with postoperative albumin, suggesting that identification of hypoalbuminemia could be used to alert clinicians about postoperative care needs." (PMID 33925831, 2021). "In another study that reviewed 109 patients with hypoalbuminemia, those with higher albumin levels at the time of admission were less likely to develop acute respiratory distress syndrome (ARDS), be admitted to the intensive care unit, and be readmitted within 90 days after discharge." (PMID 34754682, 2021). "A similar experience concerning the need for long-term administration to reach a constant albumin serum level within the normal range was also previously made in a small group of 10 patients with decompensated cirrhosis and hypoalbuminemia this is resistant to diuretic therapy." (PMID 34281177, 2021). "Third, hypocalcemia due to hypoalbuminemia may affect these results and it is better to correct the amount of serum calcium according to albumin level." (PMID 34475485, 2021). "Albumin in CPB priming prevents CPB-induced hypoalbuminemia and may reduce endothelial glycogalyx destruction and, thus, it may maintain microcirculatory function better." (PMID 32111230, 2020). "We hypothesized that oxidized modifications of albumin, i.e., thiolation, explain the role of hypoalbuminemia as a predictor of cardiovascular morbidity and mortality." (PMID 32824562, 2020). "For example, in CanL, nonregenerative normocytic normochromic anemia, leukogram changes (i.e. neutrophilia), trombocytopenia and dysproteinemia (i.e., hyperproteinemia, hyperglobulinemia, hypoalbuminemia, inversion in the albumin/globulin ratio) represent typical laboratory findings." (PMID 32571332, 2020). "Albumin injection in hypoalbuminemia patients can affect the levels of serum albumin." (PMID 32727558, 2020). "Finally, this study also shows that those hospitalized LF-infected patients with hypoalbuminemia and/or reversal of albumin-to-globulin ratio tend to have leucocytosis and experience prolonged duration of illness." (PMID 33312698, 2020).
Hypoalbuminemia (continued). "Combined hypoalbuminemia (albumin level < 2.8 g/dL) and low BMI (<18.5 kg/m2) may be a useful prognostic indicator of high mortality risk in elderly individuals with limited performance status." (PMID 31945744, 2020). "In contrast, hypoalbuminemia is also reported that could be due to disruption in liver function that leads to a decrease in albumin synthesis during Babesia infection." (PMID 33132601, 2020). "Proinflammatory cytokines were inversely correlated with serum albumin in patients treated with peritoneal dialysis, suggesting hypoalbuminemia could be regarded as a marker of inflammation in dialysis patients." (PMID 32059708, 2020). "Due to marked hypoalbuminemia and anemia, packed cell and albumin were transfused." (PMID 33167916, 2020). "Hypoalbuminemia, frequently caused by the impaired synthesis in the scenario of advanced cirrhosis, may further deteriorate after GIB due to the direct loss of albumin in the gastrointestinal tract and short-term fast." (PMID 32576140, 2020). "Understanding the link between inflammation, hypoalbuminemia, and poor outcome in SCD patients could help identify at-risk patients and define novel mechanistic applications of serum albumin in SCD." (PMID 32776978, 2020). "According to a past report, hypoalbuminemia was defined as serum albumin ≤3.5 g/dL." (PMID 32778080, 2020). "Hypoalbuminemia is the level of albumin lower than 40.0 g/L." (PMID 33243215, 2020). "Importantly, in one of the study, hypoalbuminemia, a condition of reduced albumin levels have been detected as a marker of the advanced stage as well as higher cancer burden in MM patients." (PMID 33585190, 2020). "The socio-demographic analysis revealed that the serum albumin level was significantly lower in patients who were less educated, with illiterate patients or those having primary or intermediate education presenting hypoalbuminemia." (PMID 33261019, 2020). "The comparison of the albumin values between the baseline and follow up showed an improvement only in 8.6% of the sample, while in 91.4%, the values remained stable; in addition, only 2.9% of subjects had hypoalbuminemia at the baseline." (PMID 32575448, 2020). "The hypoalbuminemia may be a consequence of albumin uptake anddegradation by the parasites during intraerythrocytic growth, anddifferentiation." (PMID 32022168, 2020). "Albumin concentrations were significantly lower in the deceased group than in the discharged group, with 38% (13 of 34) deceased patients and 10% (17 of 172) discharged patients developed hypoalbuminemia." (PMID 32651993, 2020). "In the current study serum IL-6 level was strongly correlated with various clinical inflammatory parameters (serum CRP, hemoglobin, and albumin levels), and the prevalence of anemia, hypoalbuminemia, and CRP elevation were significantly greater in the higher IL-6 group than in the other two groups." (PMID 31951598, 2020). "Albumin less than 3.5 g/dL is recognized as hypoalbuminemia (malnourished)." (PMID 33203417, 2020). "We know that stress and infection are associated with hypoalbuminemia, with an increase in albumin clearance, rather than decreased albumin synthesis, being dominant." (PMID 32819439, 2020). "Moreover, more patients with hypoalbuminemia (serum albumin ≤ 40 g/L) and lymphopenia (lymphocyte number ≤ 1.1 × 109/L) were observed in the COVID‐19 group as well (P < .05)." (PMID 32696465, 2020). "Hypoalbuminemia (albumin <3.4 g/dL) was observed in 93/238 (35.6%) patients." (PMID 32555205, 2020). "It has previously been demonstrated that albumin infusion in patients with hypoalbuminemia may accelerate wound healing by modulating the expression of transduction factors and proteins." (PMID 32518615, 2020). "In liver cirrhosis, albumin production is reduced, and hypoalbuminemia results in reduction of circulating blood volume, which may cause various complications." (PMID 32051434, 2020).
Hypoalbuminemia (continued). "Additionally, patients with hypoalbuminaemia were significantly older than patients with normal albumin levels (mean 39.3 ± SD 18.3 versus 31.1 ± 14.4, p = 0.008)." (PMID 32029855, 2020). "*Albumin level 35-50, any level less than 35 is considered as hypoalbuminemia." (PMID 32879825, 2020). "Although serum albumin levels are increasingly used as an indicator of nutritional status in the clinic, the relationship between perioperative hypoalbuminemia and wound complications after posterior lumbar interbody fusion in the treatment of lumbar degenerative disease remains ambiguous." (PMID 33203417, 2020). "In particular, the cat showed hypochromic and microcytic anaemia, while the protein profile analysis highlighted hyperproteinemia and alteration of electrophoresis with hypergammaglobulinemia, hypoalbuminemia and, consequently, a reduced albumin/globulin ratio (0.2)." (PMID 30909954, 2019). "Hospitalized patients with mild hypoalbuminemia (albumin 25–35 g/L) were older, lower body mass index, and more hypertension, congestive heart failure and chronic renal failure than those with normal albumin levels." (PMID 31253199, 2019). "Furthermore, patients in the hypoalbuminemia group were 2.7 times more likely to have poor neurologic outcome than were those in the normal albumin group (model II)." (PMID 31565439, 2019). "The vast majority presented with nephrotic syndrome (613/752, 81.5%), hypertension (466/752, 61.9%), hypoalbuminaemia, defined as serum albumin levels<3gr/dL, (481/752, 63.9%) and dyslipidaemia, defined as serum cholesterol >250mg/dl and/or serum triglycerides >160mg/dl, (482/752, 64%)." (PMID 31404062, 2019). "However, there is limited data about the effects of mild hypoalbuminemia with small decreases in albumin on postoperative complications." (PMID 31253199, 2019). "Although the exact mechanisms of hypoalbuminemia in aSAH patients remain elusive, a pilot study revealed that 1.25 g/kg/day albumin treatment was safe in SAH patients and might produce a better outcome." (PMID 31781024, 2019). "As a result, the presence of low ALB or hypoalbuminemia may lead to impairment of immunity and poor anti-cancer responses." (PMID 31632493, 2019). "Fourth, oxidative modifications of serum albumin could also lead to “fictitious” hypoalbuminemia due to the underestimation of actual albumin levels using the BCG method in this study." (PMID 30911552, 2019). "and 45.2% with ehrlichiosis only had hypoalbuminaemia as measured by a decreased value of albumin." (PMID 31885847, 2019). "Put altogether, dosing prediction using total concentration targets would result in unnecessarily high doses in patients with hypoalbuminemia and progressively lower doses with increasing albumin concentration, which are sub-optimal, when compared to predictions with the unbound target." (PMID 31171022, 2019). "Most patients 145 (79.7%) had hypoalbuminemia on admission (albumin < 35 g/dl)." (PMID 31847847, 2019). "However, the mean SZC in patients with hypoalbuminemia was significantly lower (67.8 μg/dL, p = 0.012) than patients with normal serum albumin (80.6 μg/dL)." (PMID 31694220, 2019). "Finally, it showed that the ratio increased with worsening hypoalbuminemia from 4.5:1 for an albumin under 3 g/dl to 13.1:1 for an albumin under 2 g/dl in patients with low bleeding risk." (PMID 31269849, 2019). "Albumin accounts for about 80% of colloid osmotic pressure, thus increasing the vascular hyper-permeability of the inflammatory state, leading to a decrease in oncotic pressure in patients with hypoalbuminemia and thus a reduction in intravascular volume." (PMID 32025402, 2019). "Urinary albumin excretion, hypoalbuminemia, elevated BUN, serum Cr, urine glucose, and decreased GFR levels occurred in DN, which may be related to T2DM and formation of free radicals." (PMID 32133060, 2019).